CCR10 (C-C motif chemokine receptor 10)
Diseases named in the same sentence as CCR10 in open-access papers (continued):
Sharing a sentence is not in itself a finding about the gene and the disease.
tumor (continued). "In contrast, in human ovarian and liver tumors, hypoxia favors the production of high CCL28 levels by tumor cells that are correlated with poor patient survival and with the recruitment of CCR10-expressing Tregs in the TME." (PMID 33924428, 2021). "Hypoxia promotes tumor cells to express a large amount of CCL28 receptors, which recruit Tregs into tumor tissues and interact with CCR10 on Tregs surface to exert immunosuppressive effect." (PMID 34977159, 2021). "In a murine model of ovarian cancer, the overexpression of CCL28 by tumor cells favors a preferential recruitment of CCR10+ Tregs, resulting in an accelerated tumor growth." (PMID 33924428, 2021). "Incubating tumor cells with a neutralizing antibody for CCL27, one of the ligands of CCR10, prevented tumor formation." (PMID 30420855, 2018). "We found that CCR6 and CCR10 were the only chemokine receptors that were more highly expressed by the CD39+ Treg in the tumor compared to the CD39− Treg." (PMID 30651930, 2018). "CCR6 and CCR10 are implicated in Treg homing to tumors, and were more highly expressed by the CD39+ Treg in the tumor." (PMID 30651930, 2018). "Nine months after DEN treatment, tumor counts and sizes were both significantly reduced in CCR10 KO mice relative to WT mice." (PMID 29445190, 2018). "Here, we initially observed elevated levels of pro-inflammatory cytokines (most notably TNF), infiltration of inflammatory cells, and upregulation of four GPCR-associated genes (CCR10, P2RY8, ARRB1, and RGS10) in human HCC tumor and paracancerous specimens." (PMID 29445190, 2018). "Hepatocytes isolated from HCC tumor tissue and matching paracancerous tissue in CCR10 KO mice showed significantly lower Akt phosphorylation and PCNA expression relative to hepatocytes isolated from their WT counterparts." (PMID 29445190, 2018). "Through RT-PCR and Western blotting validation, we confirmed that CCR10 expression was significantly elevated in hepatocytes isolated from matching human HCC tumor and paracancerous specimens." (PMID 29445190, 2018). "CCL22 and CCL28, expressed in many human tumors, are mediators for the recruitment of CCR4+/CCR10+ Treg cells, involved in the suppression of both spontaneous and therapy-induced local tumor immunity." (PMID 30319638, 2018). "These drugs perform two important functions for these cells; first, they increased their cytotoxicity against tumor cells, and second, they upregulate the expression of CCR10 on their surfaces." (PMID 27807435, 2016). "Hypoxia-induced CCL28 secretion by the tumor has been shown to induce the CCR-10-dependent recruitment of Treg to tumors, exacerbating the immunosuppressive pressure that allows the tumor to evade host destruction." (PMID 27066484, 2016). "It is also demonstrated that these three drugs enhance NK cell cytotoxicity against tumor target cells, an activity that is abrogated by prior incubation of the cells with anti-CCR10 antibody." (PMID 27807435, 2016). "NK cells either untreated or incubated with 10 μg/mL anti-CCR10, or as a control with isotype control IgG antibody, were examined for their ability to lyse tumor target cells in the NK cytotoxicity assay." (PMID 27807435, 2016). "Intratumoral administration of CCR10 as well as other chemokine-expressing adenoviral vector into tumor-bearing animals resulted in the recruitment and activation of T cells at sites of tumor growth." (PMID 27807435, 2016). "Having established that CCR10 activation promote proliferation and invasion in vitro, we evaluated the contribution of CCL27/CCR10 signaling on tumor growth in vivo by using experimental intracranial models." (PMID 25149529, 2014). "Pearson's chi-squared test demonstrated that CCR10 in tumor tissues positively correlated with p-Akt expression." (PMID 25149529, 2014). "Among the 5 upregulated receptors, we focused on CCR10, which was known for tumor development in plenty of cancers." (PMID 25149529, 2014).
tumor (continued). "It has been shown that increased expression of CCL28 during angiogenesis allows recruitment of the CCR10+ T-regulatory cells, which protect tumor cells from immune clearance and increase tumor angiogenesis and vascularization." (PMID 24384839, 2013). "Insights into the temporal regulation of CCR10 during tumor evolution, combined with its conserved features across mammalian species, may inform the design of targeted immunotherapies." (PMID 41050670, 2025). "Interestingly, the off-tumor expression of CCR10 was comparable to the expression of other MM targets currently under investigation (e.g., SLAM7 and CD138), suggesting a potentially favorable safety profile." (PMID 40597436, 2025). "Several other studies highlight the PI3K/Akt pathway, as crucial in CCR10-mediated interactions across various cancers, including skin, liver, lung, and brain, where it contributes for cancer progression regulating tumor cell survival, proliferation, and metabolism." (PMID 41050670, 2025). "Additionally, CCR10 contributes to various cancers both through its expression directly on malignant cells and by its expression on cells in the tumor microenvironment." (PMID 40975172, 2025). "Moreover, they express chemokine receptors, such as CCR4, CCR5 and CCR10, which facilitate chemotactic migration of Tregs into the tumor microenvironment." (PMID 38500876, 2024). "Immunohistochemical validation of tissue samples from CRC patients was showed that mildly positive CCR10 and XCR1 expression could be observed in tumor tissues, but higher CCR10 and XCR1 expression was observed in normal tissues." (PMID 39835121, 2024). "The researchers used single-cell analysis to further elucidate the role of the expression levels of the CCRs in the tumor-infiltrating immune cells in GC and observed that the T-cells and the macrophages were highly expressed in the CCRs when the CCR10 expression was high in plasma cells." (PMID 38169378, 2024). "In hypoxia, for instance, hypoxia enhances the secretion of CCL28 by tumor cells in a HIF-1α-dependent mode, which enhances the recruitment of CCR10+ T reg cells to the tumor site, thus inhibiting the functions of cytotoxic T cells and accelerating tumor growth." (PMID 38165484, 2024). "Regulatory T-cells inhibit anti-tumor immunity and promote tumor development and progression, so suppression of CCR10 in vorinostat-treated Myla cells could indicate less Treg activity and a more robust anti-tumor response." (PMID 37175780, 2023). "Conversely, CCR1 and CCR10 were found upregulated in GBM infiltrating area compared to the tumor core, which suggests a role for these receptors at the margin of the tumor, probably linked to cell invasion or communication with the tumor microenvironment (TME)." (PMID 35008294, 2021). "In addition, it has been reported that hypoxia induces the expression of CCL28, a CCR10 ligand, by tumor cells of ovarian and liver cancers, which recruits CCR10-expressing Treg cells into tumor tissues." (PMID 34885241, 2021). "CCR10 antagonist (brintonamide D) demonstrates a potential anti-tumor effect in breast cancer." (PMID 34806028, 2021). "Here we describe that CCL28/CCR10 axis could be active outside the tumor core and that it could represent a connection between the margin of the tumor and the peripheral healthy tissue." (PMID 33066172, 2020). "Moreover, exogenous CCR10 expression significantly raised xenograft tumor growth in Balb/c nude mice." (PMID 29445190, 2018). "CCR10 KO mice showed a significantly lower liver weight/body weight ratio, significantly lower tumor incidence, and significantly lower mean and maximal tumor sizes relative to WT mice." (PMID 29445190, 2018). "Moreover, implantation of CCR10-transfected Hep3B xenograft tumors in nude mice significantly promoted in vivo tumor growth." (PMID 29445190, 2018).
tumor (continued). "Similar to its effect on GA-enhanced NK cell cytotoxicity, incubating activated NK cells with anti-CCR10 for 45 min abrogated the cytotoxicity induced by MMF or DMF against K562 cells or MMF-enhanced activated NK cell cytotoxicity against RAJI tumor cells." (PMID 27807435, 2016). "We observed that anti-CCR10 reduced NK cell lysis of tumor target cells." (PMID 27807435, 2016). "A 10% increase after treatment with the drugs described in this manuscript suggests that the number of CCR10+ NK cells might be increased to about 200–500 × 108/5 L of blood; a substantial number of killer cells that may potentially inhibit tumor growth." (PMID 27807435, 2016). "Finally, we also certified that CCR10 in tumor tissues positively correlated with p-Akt expression in GBM clinical samples." (PMID 25149529, 2014). "In vivo, CCR10 shRNA treated LN229 cells displayed a marked reduction of the tumor." (PMID 25149529, 2014). "We focused on CCR10, which was known for tumor development in plenty of cancers." (PMID 25149529, 2014). "CCR10 shRNA treated LN229 cells displayed a marked reduction of the tumor." (PMID 25149529, 2014). "In addition, MMP9 and Ki67, markers of tumor invasion and proliferation were also suppressed by CCR10 shRNA." (PMID 25149529, 2014). "Other chemokine receptors implicated in Treg trafficking to tumor sites include CXCR4, which drives Treg cells toward tumor site via interactions with CXCL12 that is produced within the tumor microenvironment, as well as CCR8 and CCR10 (86, –88)." (PMID 23874336, 2013). "Numerous reports have described a role of CCR10 and its ligands in cancer although the benefits of CCR10 antagonism may be cancer-dependent: the receptor can have protumoral effects when expressed on regulatory T cells or tumor cells or antitumoral effects when expressed on CD4+ and CD8+ T cells." (PMID 40975172, 2025). "Accordingly, this review discusses CCR10’s molecular characteristics, phylogenetic background, functional roles in immune cell trafficking, and its involvement in the pathogenesis of inflammatory and neoplastic diseases, based on a systematic search of the literature." (PMID 41050670, 2025). "Notably, CCR10 could also potentially inhibit tumor growth and metastasis by modulating processes related to invasiveness and epithelial-mesenchymal transition (EMT), making it a dual player in cancer biology." (PMID 40597436, 2025). "CCR10 can facilitate infiltration of central and effector memory T cells into tumors, and strategies that increase chemokine expression may boost immune responses in the tumor microenvironment." (PMID 41050670, 2025). "Our analyses showed that CD8+ T cells, which are directly associated with tumor immunotherapy response, as well as T cells were more highly expressed at higher levels of all four molecules; B cells were also more highly expressed at higher levels of XCR1, CCR10, CXCL13, CXCR6." (PMID 39835121, 2024). "Thus, the CCL28-CCR10 axis may have significant pro-tumor activities in the hypoxic tumor microenvironment by inducing angiogenesis via VEGF and attracting CCR10-expressing Treg cells." (PMID 34885241, 2021). "Moreover, CCR10 significantly raised xenograft tumor growth in Balb/c nude mice." (PMID 29445190, 2018). "Hence, anti-CCR10 or PTX might interfere with such interaction resulting in inhibiting NK cells mediating lysis of tumor cells." (PMID 27807435, 2016). "However, CCR10 was mostly expressed on the inflammatory cells in tumor stroma." (PMID 27250766, 2016). "Lymphatic endothelial cells (LECs) expressing CCR10, regulated by VEGF-D and TNF-α migrate towards tumor-derived CCL27 and CCL28; VEGF-D is essential for in vivo lymphatic vessel formation and metastasis." (PMID 41050670, 2025). "Plasmodium infection blocks the TGFβ/CCR10/PI3K/Akt/GSK-3β signaling pathway, thereby inhibiting epithelial–mesenchymal transition (EMT) of the cancer cells and preventing tumor metastasis and recurrence." (PMID 38807760, 2024).
tumor (continued). "In tumor tissues under hypoxic environments, CCR3 expressed in vascular endothelial cells, and CCR10 expressed in Treg cells, both receptors for CCL28, have been reported to contribute to promoting the angiogenesis process through hypoxia-induced CCL28." (PMID 38534417, 2024). "CCR4, CCR8, CCR10, and CXCR3 induce Treg cell migration to the tumor microenvironment in response to CC and CXC chemokines: CCR4 is bound by CCL17 and CCL22, CCR8 is bound by CCL1, CCR10 is bound by CCL28,and CXCR3 is activated by CXCL9/10/11." (PMID 36012113, 2022). "The results above delineate the alteration of SPTBN2 and BCL2L1 in view of tumor immune modulation mediated by CCL27 and CCR10, resulting in a reduced abundance of CD4+ T cells and dendritic cells." (PMID 34179092, 2021). "By binding to its receptor, CCR10, CCL28 can effectively recruit CCR10+ Treg cells to the tumor site, thus suppressing the functions of effector T-cells and promoting the tumor growth." (PMID 33422072, 2021). "Then, we used flow cytometry to label and analyze the number of CCR3+, CCR9+, CCR10+, CXCR2+, CXCR5+, and CXCR6+ cells expressed different isotype antibodies including IgA, IgG, and IgM in the lung metastases of cKO and control tumor-bearing mice." (PMID 33707428, 2021). "CCR10 interacted with CCL28 to mediate the recruitment of Treg into tumors and accelerated tumor progression." (PMID 33868236, 2021). "Consistent with our short-term findings, HCC tumor tissue and matching paracancerous tissue in long-term DEN-treated CCR10 KO mice displayed significantly lowered hepatocellular Akt phosphorylation and PCNA expression." (PMID 29445190, 2018). "In vivo, hepatocytes isolated from HCC tumor tissue and matching paracancerous tissue in DEN-treated CCR10 KO mice showed significantly lower Akt phosphorylation and PCNA expression relative to WT hepatocytes." (PMID 29445190, 2018). "Since, induced FoxP3 are downregulated for CCR7 and CD62L as well as upregulated for memory or effector-type trafficking receptors such as CCR4, CCR5, CCR8, CCR10, and/or CXCR4, they can migrate into the tumor via the tumor-draining lymph nodes." (PMID 29450136, 2017). "CCR 6, CCR 10, CXCR 3, and CXCR 4 are important members of the chemokine receptor family, which play important roles in cell migration, immune response, inflammation, as well as tumor growth and metastasis." (PMID 40332418, 2025). "Tumor cells and stromal cells recruit Tregs to the tumor site primarily by secreting chemokines such as CCL22, CCL17 (binding to CCR4 on Tregs), and CCL28 (binding to CCR10)." (PMID 40698080, 2025). "By analyzing the effect of MAP2K3 expression levels on chemokines in the tumor immune microenvironment, the results showed elevated expression of several chemokines in the MAP2K3 high expression group; such as CXCL10, CCR5, CCR10, CCL5, CCL7, CCR2, and CCL22 (upper part)." (PMID 38938778, 2024). "In addition, tumor-infiltrating Treg cells showed distinct expression of chemokines and chemokine receptors, e.g., IL-8 (CXCL8), CX3CR1, CXCR7, and CCR10, some of which have been proposed as a prognostic marker and/or therapeutic target in cancer." (PMID 33976194, 2021). "Tumor associated macrophages (TAMs) and myeloid suppressor cells (MDSCs) release chemokines, such as CCL17, CCL22, CCL5, CCL6 or CCL28, depending on the tumor type, to attract Tregs expressing the chemokine receptors CCR4, CCR5, CCR10 and CXCR3 from secondary lymphoid tissues to the tumor." (PMID 32937953, 2020). "Strikingly, patients with metastatic sentinel lymph nodes had higher levels of CCR10 expression on primary tumor cells than patients with negative sentinel lymph node." (PMID 30420855, 2018). "CCR10, the receptor for the chemokines CCL27/CTACK and CCL28/MEC, belongs to the chemokine receptor subfamily of GPCRs and is thought to function in immune responses and tumour progression." (PMID 26941067, 2016).
tumor (continued). "The chemokine receptors, CCR10 and CCR4, known to respond to chemo-attractants CCL27, MCP-1, and CCL22, have been shown to be critical in inducing mobilization and homing of myeloid cells and leukocytes to the tumor site." (PMID 23372791, 2013). "Interestingly, different chemokine receptors direct tumor cells to specific organs in a mouse model, for example, CCR7, CCR10, and CXCR4 to lymph node, skin, and lung metastasis, respectively." (PMID 23342280, 2012). "Notably, chemokine receptors, including C-C chemokine receptor type 2, 4, 5, 6, 8, 10 (CCR2, CCR4, CCR5, CCR6, CCR8, CCR10), and C-X-C chemokine receptor type 3, 4 (CXCR3, CXCR4) have been identified as significant factors in the recruitment of Treg cells to the tumor site." (PMID 39000453, 2024). "While CCL28 has both anti- and pro-tumor properties, the latter dominate in the hypoxic cancerous Tumor Micro-Environment (TME) and involves stimulating the chemotaxis of myofibroblasts and various lymphocyte types, including Tregs, to the tumor site via CCR10 activation." (PMID 36841432, 2023). "CCR10 and its ligand CCL28 are known to participate in the recruitment of tumor TReg lymphocytes, and a decrease in CD4+ CCR10+ cells may reflect a reduced global presence of CCR10-expressing TRegs and, therefore, a reduced recruitment of these cells by the tumor." (PMID 35740564, 2022). "For example, CCR10 expression does not appear to change significantly with disease stage, although CCL27 levels are lower in patch lesions compared to plaque and tumor-stage lesions." (PMID 40861461, 2025). "To conclude, except for CCR6 and CCR10, CD39+ and CD39− Treg in tumors have a largely similar chemokine receptor expression, and chemokine receptor usage alone can probably not explain the preferred accumulation of CD39+ Treg in the tumor." (PMID 30651930, 2018).